IL10 (interleukin 10)
Diseases named in the same sentence as IL10 in open-access papers (continued):
Sharing a sentence is not in itself a finding about the gene and the disease.
tumor (continued). "In both the tumor and spleen of the ApcMin/+ mice, IHS strongly suppressed the expression of IL-5 (p < 0.05), IL-6 (p < 0.05), IL-10 (p < 0.05), P-JAK1 (p < 0.05), P-JAK2 (p < 0.05), P-STAT3 (p < 0.05), and P-STAT5 (p < 0.05) and enhanced the P-STAT1 expression (p < 0.01)." (PMID 36014805, 2022). "Secondary endpoints defined as tumor tissue infiltration with CD4+, CD8+ T-cells and CD20+ B-cells, lymphocytic response measured through cytokine concentrations (e.g., NFα, IFN-γ, RANTES) and antibody response (e.g., IL-10, IL-6) in patients’ blood, prostate and skin biopsies were positive." (PMID 36428811, 2022). "Moreover, the IL-10 showed an immunosuppressive role on circulating dendritic cells in HCC patients, which may indicate tumor immune evasion." (PMID 35056005, 2022). "The serum levels of VEGF, IL-8, and IL-10, as well as the expression of RIP2 and PIK3CA in tumor tissues, were highly correlated to clinical features of DLBCL, and high expression level of these indexes may have adverse effects for the prognosis of DLBCL patients." (PMID 36567775, 2022). "Interestingly, PI3Kγ is a key regulator of TAM-mediated immunosuppression, and its selective inhibition increases MHC-II and IL12 expression and decreases IL10 in TAMs; as well as helping to overcome resistance to ICI, reshaping the TME and promoting CD8+ T cell recruitment and tumor regression." (PMID 35664746, 2022). "However, the effect of IL-10 may vary depending on the tissue context as it can even trigger IFN-γ secretion and increase cytotoxic anti-tumor lymphocytes and tumor rejection." (PMID 36500861, 2022). "Another study of combined treatment with neutralizing antibodies against IL-10 and CAR-T in 38 patients with MSS liver metastatic CRC showed that IL-10 increased CEA-specific CAR-T cell activation and promoted CAR-T mediated tumor cell death, inducing nearly 70% apoptosis in tumor biopsies." (PMID 36275766, 2022). "In contrast to C4-Mye enriched in blood, C6-Mye preferred tumor and paratumor tissue and highly expressed 591 genes, including the M2 macrophage marker gene MCR1 (CD206), and highly expressed the M2 macrophage-related protumorigenic genes TGF-β, IL10, VEGFA and MMP9." (PMID 35562760, 2022). "Notably, the anti-inflammatory cytokine IL10 was not upregulated indicating a shift toward a pro-inflammatory anti-tumor microenvironment." (PMID 36418317, 2022). "Additionally, several immunosuppressive cells, including Treg, Breg, MDSC, and Kupffer cells, inhibit immune cell activity by producing cytokines such as TGF-β and IL-10 and inducing key factors in CD8+ T and NK cell depletion, leading to immune escape of HBV and HCC tumor cell." (PMID 36281288, 2022). "Extensive studies suggest that MSCs inhibit both T cells proliferation by secreting Prostaglandin E2 (PGE2) and programmed death ligand-1 (PD-L1) and T cells anti-tumor immunity by secreting immunosuppressive cytokines, such as IL-4 and IL-10, which are not necessarily related to the MSC source." (PMID 35842634, 2022). "Inhibits anti-tumor T-cell response, leading to progression of cancer through a modulatory effect on miR-21, which increases level of prostaglandin E2 and IL-10, although the exact mechanism is not clear.Stimulates expression of NF-κB gene through miRNA, which results in inflammation." (PMID 36341463, 2022). "However, in advanced tumors, anti-inflammatory mediators released in the TME, such as CSF-1, CCL2, IL13, IL4, IL10, and prostaglandin E2 (PGE2), can revert the anti-tumor program and favor a switch of TAM into an M2 phenotype with pro-tumor and immunosuppressive functions." (PMID 35163420, 2022). "Intriguingly, decreased gene expression of both pro- (Il-1β and Il-6) and anti-inflammatory (Il-10 and Tgf-β) players, as well as T CD8+ dependent effector function genes such as granzyme (Gzma) and perforin (Prf1) in TME of Opn4KO was found when compared to Opn4WT tumor-bearing mice." (PMID 35562405, 2022).
tumor (continued). "As well, on the side of TAMs that are educated by EZH2 inhibitor-treated BC cells, the increased IL-10 secretion stimulates EGFR-SRC signaling to enhance cell motility and the increased VEGF secretion accelerates vasculature development, which contribute to tumor metastasis all together." (PMID 36038549, 2022). "Therefore, even without tumor cells arriving, Lin28B enables the pre-metastatic niche to produce IL-6 and IL-10, which is enough to induce N2 conversion." (PMID 35173168, 2022). "The infiltration of inflammatory cells and an environment enriched in various cytokines (TGF-β, IL-6, IL-10, granulocyte-macrophage colony-stimulating factor (GM-CSF), IL-1β, IL-23, and TNF-α) and chemokines (“chemotactic cytokines”) may be utilized by tumor cells." (PMID 36142391, 2022). "Additionally, IL-10 and TGF-beta might be potential new targets for anti-tumor immunotherapy in patients with high-m6AlncRNAscore, deserving further study." (PMID 36241866, 2022). "It is worthwhile noting that a large panel of cytokines including MCP-1, M-CSF (CSF-1), IL-3, IL-10, IL-12, IL-16, MIP-1β, RANTES, TNF-α and TGF-β2 were upregulated resulting from autocrine effect in POSTN-overexpressing SKOV3 cells leading to potent enrichment of TAMs in the tumor microenvironment." (PMID 36550569, 2022). "Additionally, astrocytes also encourage the release of degradative enzymes, anti-inflammatory cytokines (including TGFβ, IL10, and G-CSF through activation of the JAK/STAT signaling pathway), chemokines, and growth factors, which eventually promote tumor cell growth, survival, and invasion." (PMID 36276147, 2022). "Pursuant to this, we reasoned that CM-272-induced sustained IFN-I/II signaling and/or factors like IL-10 and TGF-β could indeed hinder tumor antigen presentation by tumor-resident DCs, thereby restraining successful combination therapy of CM-272 and PD-1 inhibition." (PMID 35634329, 2022). "Similarly, iWAT of C26 tumor-bearing animals exhibited higher expression of Arg1 (6.6-fold), Il-10 (2.4-fold), and Tgfß3 (1.8-fold) but not of Tgfß1 and -2 and iNos mRNA levels compared with control mice." (PMID 35210363, 2022). "Thus, co-stimulatory αCD28 bispecific antibodies were demonstrated to efficiently counteract immunosuppressive effects of IL-10 and TGF-β on anti-tumor cytotoxic responses as well as on T cell activation, proliferation, cytokine secretion and expansion of central memory effector T cells." (PMID 34484225, 2021). "Tregs express immunoregulatory molecules (PDL1 and CTLA4) and produce immunosuppressive cytokines (IL-10, IL-35, TGF-β), which inhibit the synthesis of TNF-α, IFN-γ and IL-17 in Th1 and Th17 cells and reduce the production of perforin and granzymes in CTLs, alleviating their anti-tumor properties." (PMID 34830312, 2021). "Taking into account tumor structure, we asume that an increased level of IL-10 in non-metastatic disease (stages I, II, III) could be predominantly a result of Th2 cells secretion." (PMID 35008550, 2021). "In the meantime, TAMs as well as IFN-γ, TNF-α, IL-10 and especially IL-6 secreted by TAMs induced the expression of PD-L1 both in the cell membrane and in the cytoplasm of ovarian cancer cells, which inhibited the function of CD8+ T cells and promoted tumor growth." (PMID 34717710, 2021). "Moreover, in B16 tumor-bearing Fats−/− mice, serum levels of proinflammatory cytokines (IFN-γ, IL-12, and IL-1β) were increased, while the level of the anti-inflammatory cytokine IL-10 was significantly decreased." (PMID 34262035, 2021). "Moreover, IL-6, IL-10 and VEGF, produced by cancer cells, may activate STAT3 in a paracrine fashion in the cells present in the tumor microenvironment, such as myeloid cells or fibroblasts, transforming them into cells that support tumor growth." (PMID 33513694, 2021).
tumor (continued). "With known M2 predominance in the advanced CRC stage, increased levels of IL-10 in stage IV could be a result of M2 macrophages secretion but also MDSC and Treg cells production, as the number of these cells increases with the tumor stage." (PMID 35008550, 2021). "Previous research demonstrated that M2 macrophages could secrete several immune suppressors such as IL-10 and TGF-β and could downregulate IL-12 and IL-6, contributing to the suppression of T-cell activation and proliferation in tumor microenvironment, as well as inducing the infiltration of Tregs." (PMID 34650972, 2021). "Moreover, MSCs injected 14 days after tumor induction induced the generation of an immunosuppressive phenotype in CD4+T lymphocytes and prevented the trans-differentiation of TGF-β and IL-10-producing Tregs into anti-tumorigenic IFN-γ- and IL-17-producing Th1 and Th17 cells." (PMID 34830312, 2021). "In tumor immunity, M1 macrophages produce inflammatory cytokines such as tumor necrosis factor α (TNF-α), IL-6 and IL-12, and exert an anti-tumor effect, whereas M2 macrophages produce immunosuppressive cytokines such as IL-10 and TGF-β, and inhibit anti-tumor immune reactions." (PMID 34359568, 2021). "While IL-10 production was detected in a relatively small proportion of the CD8+CD103+ cells, it suggested a possible upregulation of an immunosuppressive phenotype by tumor-infiltrating CD103+ TRM, therefore expression of the inhibitory markers CD39, CTLA-4 and PD-1 was investigated." (PMID 33479027, 2021). "Firstly, flow cytometry analysis of glutamine-addicted RCC shows that TAMs induced by tumor-activated HIF1α could secrete IL-23, promoting the proliferation of Tregs and the expression of IL-10 and TGF-β, inhibiting the cytotoxic lymphocytes from killing tumor cells." (PMID 34625124, 2021). "Furthermore, tumor antigens in the TME may simultaneously activate extracellular signal-regulated kinase and p38 these two MAPKs, increasing IL-10 secretion, tilting Th1 response toward Th2 response, and consolidating M2/Th2-mediated immune escape." (PMID 34625124, 2021). "However, pathological analysis of the tumor microenvironment confirmed that the adaptive immunosuppressive response was simultaneously activated with increased expression of inhibitory molecules (PD-L1, TGF-β, IDO, and IL-10) and infiltration of Tregs." (PMID 33741903, 2021). "However, IL-4 and IL-10, defined as anti-inflammatory cytokines in DII calculation, could pose both anti-cancer and pro-cancer actions in the tumor microenvironment depending on the specific molecular and cellular context." (PMID 34684331, 2021). "We further found that ITGA3 was negatively correlated with monocyte markers (CD86), TAM markers (CCL2 and IL10), and M2 macrophage markers (CD163 and MS4A4A), suggesting that ITGA3 could regulate the polarization of TAMs and promote tumor growth and metastasis." (PMID 34094951, 2021). "Our data revealed that hypoxic TAMs but not tumour cells were the predominant source of IL-10." (PMID 33484377, 2021). "IL-10, TGF-1, and prostaglandin E2 in the TME can inhibit the expression of MHC-II molecules on the surface of macrophages, so the macrophages cannot effectively present tumor antigen to T cells and hinder the specific killing reaction of T cells against tumor cells." (PMID 34819086, 2021). "Tryptanthrin effectively inhibited tumor growth in 4 T1 murine breast cancer model; modulated expression levels of nitric oxide synthase 1 (NOS1), COX-2, and nuclear factor kappa-B (NF-κB) in mouse tumor tissues; and regulated some factors such as IL-2, IL-10, and TNF-α in mice." (PMID 37789475, 2021). "Finally, it appears important to underline the cooperative action of IL-6, IL-10, and TGF-β in determining higher STAT3 activity and thus STAT3-mediated negative effects on the immune responses in the tumor stroma." (PMID 33806300, 2021).
tumor (continued). "Others have shown that the paired expression of PD-1; PD-L1 on DCs is correlated with the tumor progression, loss of positive costimulatory markers (CD80, CD86, and CD40), a lack of cytokine release (IL-12, IL-10, IL-6, TNFα, and G-CSF), and contact-dependent inhibition of T cell expansion." (PMID 34078376, 2021). "In addition, all treatments, except for CD40 stimulation treatment alone, reduced the expression of immunosuppressive cytokines including IL-10 and TGF-β, in the tumor tissues, compared with control treatment with IgG, verifying the reversal of Mφ–mediated immune suppression in GBM." (PMID 34103524, 2021). "Moreover, cytokines regulated by STAT3 in tumor microenvironment, like IL-6, IL-10, VEGF and TGF-β, trigger a positive feed-back amplification of STAT3 in multiple types of cells throughout the tumor microenvironment, finally resulting in severer tumor growth and immuno-suppression." (PMID 34502195, 2021). "Through the production of inhibitory cytokines such as IL-4, IL-10, and transforming growth factor (TGF)-β, they suppress the immune response, encourage tumor invasion, development and infiltration, enhance angiogenesis, and prevent T cells from having an effective anti-tumor impact." (PMID 34368156, 2021). "M2 macrophages secrete pro-tumorigenic, pro-angiogenic, and immunosuppressive factors such as IL10, TGFβ, and VEGFA; whereas M1 macrophages produce pro-inflammatory cytokines such as TNFα, IL1, IL12, and IFNγ, and reactive oxygen species, which prevent tumor growth." (PMID 34517894, 2021). "In contrast, upon exposure to IL-4, IL-10, and IL-13, transforming growth factor beta 1 (TGFβ1), and prostaglandin E2 (PGE2), macrophages can undergo M2 activation, which is characterized by tissue repair, matrix remodeling, and tumor promotion, and mirrors those of Th2 responses." (PMID 34300195, 2021). "Hence, we aimed for an improvement in the anti-tumor effect of combined IT by injecting either monoclonal antibodies to neutralize IL-10, TGF-β, and CSF-1R or the nor-NOHA inhibitor to block the activity of arginase." (PMID 34205330, 2021). "Moreover, IL-10 suppresses APC pro-inflammatory responses: due to its immunosuppressive effect on DCs and macrophages, IL-10 can dampen antigen presentation allowing tumor cells to evade immune surveillance." (PMID 33466674, 2021). "Interestingly, M1 cells convert into pro-tumor M2 macrophages, which unlike M1 produce high levels of IL-10 and low levels of IL-12." (PMID 33803806, 2021). "M2 TAMs produce arginase 1 (ARG1), IL-10, transforming growth factor-beta (TGF-β), vascular endothelial growth factor (VEGF), matrix metallopeptidase 9 (MMP9) and prostaglandin E2 (PGE2), thus subverting anti-tumor adaptive immunity and promoting tumor development and spreading." (PMID 34572009, 2021). "Similarly, the use of inhibitors of various pro-factors such as IL-4, IL-10, TGF-β and IL-13 may reduce the migration of TAMs toward the tumor microenvironment to a certain extent." (PMID 34717710, 2021). "Interestingly, TAMs can acquire different functional phenotypes depending on TME signals; they are capable of having either the classical anti-tumor M1 type in response to IFN-γ or lipopolysaccharide or the alternative pro-tumor M2 type by IL-4, IL-10, IL-13, TGF-β and lactic acid." (PMID 33129234, 2021). "Moreover, the finding that combined blockade of PD-L1 and IL10 further enhanced T-cell immunity 50, 51 suggests that IL13 may also have the potential to be targeted together with PD-1/PD-L1 to increase anti-tumor function." (PMID 33754038, 2021). "Moreover, both ligands also synergistically regulated CD40-CD40L crosstalk between B-ALL cells and CD8+ T-cells leading to a PEG10-mediated enhanced production of IL-10 in CD40-activated leukemic cells, which impaired tumor-specific cytotoxic T-cell (CTL) responses." (PMID 34778050, 2021).
tumor (continued). "It has been reported that IL-10 produced by MDSCs could decrease the secretion of IL-6, IL-12, and tumor necrosis factor-α (TNF-α) of macrophages, which remarkably suppress their anti-tumor activity." (PMID 35004667, 2021). "Furthermore, hypoxia-induced expression of PD-L1 increased the resistance of tumor cells to CTL-mediated lysis, and its blockade enhanced T cell activation mediated by MDSCs, together with a reduced expression of MDSCs cytokines IL-6 and IL-10." (PMID 33807260, 2021). "Our study focused on patient-derived MAFs, and although MAFs did not produce IL-10 in monoculture, they induced a robust IL-10 production of macrophages, which could be increased by preconditioning of MAFs with tumor-derived conditioned media." (PMID 34944793, 2021). "To interrogate if SCEL overexpression in tumor cells can influence adjacent stromal cells that alter TME favorable for tumor progression, we used a liquid suspension array method and found that IL-6, IL-8, IL10, and MIP-1a were markedly downregulated when SCEL was knocked down in GBC-SD." (PMID 33414368, 2021). "Identification of an IL-10 response in the absence of any IFNγ to citCp450 indicates that in addition to the Th1 responses a potential regulatory repertoire exists in the mice to a citrullinated self-antigen that is presented by B16 tumour." (PMID 34858415, 2021). "Necrosed tumor cells may contribute to an inflamed TME and also proinflammatory cytokines released by CSCs, such as IL-6, IL-8, IL-10, and IL-13 can contribute to maintaining an inflammatory and suppressive TME representing the “niche” sustaining cellular stemness." (PMID 33494389, 2021). "For these tumor types, donors with selective copy number gains of IL10 or TGFB2 were found to have a worse overall survival than that of donors without these copy number gains (p = 0.0551 for IL10 in Liver-HCC; p = 0.1 for TGFB2 in Lung-AdenoCA; p = 0.0202 for both IL10 and TGFB2 in Cervix-SCC)." (PMID 34344966, 2021). "Additionally, in the presence of CCL2 produced by CAFs, TAMs, and tumor cells, cytotoxic TILs acquire a CD4+CD25+ Tregs phenotype, which leads to secretion of the immunosuppressive transforming growth factor-beta (TGF-β) and IL-10." (PMID 33922362, 2021). "This would be consistent with an immunosuppressive tumour microenvironment where DLBCL cells may directly restrict TFH functions through increased surface PD-L1 expression and autocrine IL-10 secretion, acquiring immune evasion characteristics that resemble Breg-like functions." (PMID 34572910, 2021). "Moreover, these genes may play important roles in promoting tumor angiogenesis (CXCL13, ZAP-70, and CCL19), tissue remodeling (ITGAM and ITGB2), and immunosuppression (CD4 and IL-10) in cancer cell lines or samples." (PMID 32509861, 2020). "For the non-irradiated tumor in β2-AR KO mice, we noted a significant increase in expression of several genes including Cd28, Il2, and Zap70; genes showing the greatest decrease included genes which can inhibit effector function (including Il6 and Il10)." (PMID 32286326, 2020). "A recent study that tumor cells may upregulate non-classical HLA molecules, such as HLA-G, which can be modulated by cytokines like IL-10 and IFN-γ to evade immunosurveillance." (PMID 32083005, 2020). "Tumor-derived microvesicles obtained from colorectal cancer cells promote the differentiation of blood monocytes into macrophages with mixed features of M1/M2 polarization, induce phosphorylation of STAT1 and STAT3 and change the secretion of cytokines such as IL-10, IL-12 and TNF." (PMID 32488850, 2020). "Regardless of whether radiotherapy was used or not, endostar reduced the IL-10 content in tumor tissues (p < 0.05)." (PMID 32669133, 2020). "Also, tumor-derived VEGF, IL10, and PGE2 can all enhance the FASLG expression." (PMID 33381115, 2020).